AR (androgen receptor)
Diseases named in the same sentence as AR in open-access papers (continued):
Sharing a sentence is not in itself a finding about the gene and the disease.
prostate carcinoma (continued). "Androgen deprivation therapy (ADT) by surgical or chemical castration to decrease circulating testosterone levels and to inhibit cellular AR signaling pathway, has been successfully used in advanced prostate cancer." (PMID 34548474, 2021). "Androgens exert their effects through a protein called the androgen receptor (AR), which turns on and off genes that regulate prostate cancer growth." (PMID 33513133, 2021). "For example, in prostate cancer, prolonged exposure to androgen pathway inhibitors induce the development of aggressive disease characterized by low androgen receptor expression and response to most standards of care treatments." (PMID 34771460, 2021). "In the current study, we demonstrated that OB-secreted factors reduced AR activity, but, surprisingly, induced the growth of prostate cancer cells." (PMID 34966687, 2021). "With AR mutation or amplification, a low concentration of androgen can still activate the AR signaling pathway in CRPC, causing rapid worsening of prostate cancer in patients." (PMID 34685466, 2021). "Pathogenesis of these malignancies is characterised by dysregulation of sex hormone signalling pathways, mediated by the estrogen receptor-α (ER) in breast cancer and androgen receptor (AR) in prostate cancer." (PMID 34209750, 2021). "The Mediator subunit MED1 has been described to promote androgen-dependent AR activity through interaction with the ligand-binding domain of AR, and is overexpressed in prostate cancer." (PMID 33513133, 2021). "For example, the previous study showed that some proteins specifically bind to AR (androgen receptor) mRNA rich in the UC region and play a role in post-transcriptional regulation of AR expression in prostate cancer cells." (PMID 34496744, 2021). "FOXA1 is predominantly considered a pioneer factor for ER from studies in ER+ breast cancer as well as the androgen receptor (AR) in prostate cancer, promoting chromatin accessibility for these TFs28,34,45." (PMID 33980863, 2021). "For example, the steroid receptor RNA activator (SRA) is regarded as an AR regulator and potentiates prostate cancer progression." (PMID 33219721, 2021). "SMARCAE1 (BAF57) is elevated in a subset of tumors that, by interacting with androgen receptor, promotes prostate cancer progression." (PMID 33670012, 2021). "In almost all patients, the proliferation and growth of prostate cancer is driven by the androgen receptor." (PMID 34298700, 2021). "Once the initial tumor regression is performed with the available AR deprivation treatment, prostate cancer progresses to the castration resistant form, called CRPC." (PMID 32854238, 2020). "In castration-resistant tumors, AR acquires the capacity to drive the proliferation of cells in the absence of androgen, suggesting that AR function is essential even in advanced prostate cancer." (PMID 32296610, 2020). "HOXB13 acts as a transcription factor and, together with the androgen receptor (AR) and FOXA1, regulates expression of the RFX6 gene which encodes a driver of prostate cancer progression." (PMID 32546843, 2020). "Aberrant AR signaling is a common feature of prostate cancer, with up to 56% of primary cases and 100% of metastatic cases reported to carry genetic alterations within key AR pathway components." (PMID 32630372, 2020). "Prevalent expression of wild type CYP3A5 (*1/*1) form can promote AR activation in the AA prostate cancer patients as compared to NHWA." (PMID 32316460, 2020). "Green tea catechins, epicatechin, epigallocatechin and epigallocatechin-3-gallate were examined in the regulation of androgen receptor acetylation in androgen-dependent prostate cancer cells." (PMID 32660101, 2020). "Resistance to AR‐targeted therapy remains a major challenge in the treatment of prostate cancer, underscoring the need for novel therapeutic approaches." (PMID 32459381, 2020).
prostate carcinoma (continued). "Many preclinical and epidemiologic data corroborate the central role of androgen receptor (AR) signaling in Prostate Cancer (PCa) oncogenesis and disease progression." (PMID 32455948, 2020). "For instance, p300/CBP can promote the development of prostate cancer in an AR‐dependent transcription." (PMID 32951317, 2020). "Canonically, MYC up-regulation in luminal prostate cancer cells functions to oppose the terminally differentiating effects of AR." (PMID 32681068, 2020). "ASCT2 (SLC1A5) was shown to correlate with 14C-Fluciclovine uptake in androgen receptor-positive human LNCaP prostate cancer cells in vitro." (PMID 33237350, 2020). "The expression of miR-21 is activated by AR in human prostate cancer cells but decreases under the influence of androgens in breast cancer cells." (PMID 32373367, 2020). "Taken together, the multifunction of PMEAP1 isoforms over AR/TGF-β signaling implied a new venture of anti-prostate cancer hormone inhibitory therapy." (PMID 32842649, 2020). "In prostate cancer, androgens can stimulate cell cycle progression by AR-mediated regulation of G1–S transition, while androgen ablation triggers cell death and cell cycle arrest." (PMID 33193298, 2020). "In conclusion, this data supports our earlier observation that CYP3A5 plays a major role in AR regulation, thus modulating AR downstream signaling and prostate cancer growth." (PMID 32316460, 2020). "As a consequence, FLNA and AR interaction is a key feature in regulating androgen deprivation therapy response in prostate cancer." (PMID 32626651, 2020). "Collectively, our findings draw attention towards the widespread use of AR antagonists and the plausible emergence of a distinct resistance mechanism associated with ADT-induced SPINK1 upregulation in prostate cancer." (PMID 31959826, 2020). "AR is a well-known transcription factor that responds to male sex hormones, and controls prostate cancer development and metastasis." (PMID 32781788, 2020). "In a study done on patients diagnosed with prostate carcinoma, androgen-deprivation therapy was given by androgen receptor blockers, resulting in decreased androgen hormone levels." (PMID 32104638, 2020). "The same holds true for prostate cancer related genes, especially AR, which has frequently been discussed to be a target for treatment of TNBC patients." (PMID 33014830, 2020). "Similar to prostate cancer, ChIP-seq studies have shown that there is extensive overlap between locations of AR and FOXA1 binding in breast cancer cells." (PMID 33062889, 2020). "If advanced prostate cancer becomes androgen-independent following testosterone castration, secondary hormone treatment with androgen receptor antagonists or ketoconazole is used." (PMID 33240734, 2020). "AR is a ligand-dependent nuclear transcription factor that activates genes essential for proliferation and differentiation and is necessary for prostate cancer progression." (PMID 33182737, 2020). "For example, androgen receptor (AR) significantly elevated in prostate cancer compared with others, consistent with the known role of AR in prostate cancer development and disease progression." (PMID 33287876, 2020). "Until now, androgen deprivation therapy (ADT), which inhibits androgen receptor (AR) signalling, has been the primary treatment for early-stage prostate cancer." (PMID 32188463, 2020). "Given the dependence of prostate cancer on AR, it is essential that we identify AR-regulated genes that are involved in prostate tumor metastasis." (PMID 32296610, 2020). "Prostate cancer is originally dependent on androgen when diagnosed, and mainstay medications used are androgen-deprivation therapy, androgen receptor (AR) antagonists, and androgen synthesis inhibitors." (PMID 33158305, 2020). "The GSK-3 inhibitors maleimide SB216763 and the aminopyrazole GSK inhibitor XIII will suppress AR-transcriptional activity as well as AR expression in prostate cancer cells." (PMID 32365809, 2020).
prostate carcinoma (continued). "Preclinical studies have shown that the Bcl-2 promoter has ARE binding sites and that ligand activation of AR in prostate cancer cell lines directly represses Bcl-2 transcription and COX2 expression via modulation of NF-κB signaling." (PMID 32850312, 2020). "Castration-resistant prostate cancer exhibits resistance to androgen deprivation therapy mainly because IL-23 secreted by MDSCs activates the androgen receptor (AR) and the STAT3/RORγ signaling axis in prostate tumor cells." (PMID 32942545, 2020). "Further studies are needed to investigate the role of α-tubulin acetylation, androgens levels and AR expression, as a link between SRF inhibition and AR sub-cellular localisation in prostate cancer." (PMID 33260953, 2020). "Here, we uncovered novel molecular interactions between CHK2 and AR that provide mechanistic insight into our observation that CHK2 negatively regulates prostate cancer growth." (PMID 32579110, 2020). "In summary, our data confirm a modulating role of menin in AR-mediated gene regulation in prostate cancer." (PMID 31947537, 2020). "Mechanistically this has been observed to occur in CRPC patients and in transgenic prostate cancer models through the activation of AR signalling due to paracrine IL-23 secretion by MDSCs." (PMID 33003551, 2020). "Presently-available AR inhibitors are being widely used to treat prostate cancer and are showing encouraging results in several clinical trials in breast cancer." (PMID 31952272, 2020). "Deng X et al11 found that PRMT5 promotes prostate cancer cell growth by epigenetically activating transcription of the androgen receptor (AR) in prostate cancer cells." (PMID 31851779, 2020). "A recent study showed that auranofin promoted AR protein degradation and inhibited AR transcription, which in turn suppressed AR-positive prostate cancer cell survival." (PMID 32354165, 2020). "The androgen receptor (AR) is the main therapeutic target in advanced prostate cancer, because it regulates the growth and progression of prostate cancer cells." (PMID 33134178, 2020). "Blocking androgen receptor (AR) transcriptional activity by androgen deprivation therapy (ADT) improves the response to radiotherapy for intermediate and high risk prostate cancer." (PMID 32708219, 2020). "There is mounting evidence of androgen receptor signaling inducing genome instability and changing DNA repair capacity in prostate cancer cells." (PMID 32123273, 2020). "We have previously shown that CYP3A5 is expressed in androgen receptor positive prostate cancer cell lines (LNCaP, C4-2 and 22RV1) and promotes activation of AR and prostate cancer growth." (PMID 32316460, 2020). "It is well known that androgen receptor plays a crucial role in the regulation of the normal prostate as well as in the promotion and progression of prostate cancer." (PMID 32397108, 2020). "We established that SIRT7 promoted prostate cancer proliferation, autophagy and metastasis via the AR signaling pathway indirectly." (PMID 32019578, 2020). "To test this possibility, we compared the list of splicing events common across all stages of prostate cancer (A∩B∩C∩D) and list of splicing events induced by either pharmacological and genomic inhibition of AR in LNCaP and MDA-PCa-2b cells." (PMID 32820253, 2020). "Recent studies have revealed that IL-1 represses activity of AR in prostate cancer cells and promotes the progression of prostate cancer to androgen-independent disease." (PMID 33076397, 2020). "Histological analysis of castration-resistant prostate cancer showed a subtype of neuroendocrine transdifferentiation in an AR-independent manner." (PMID 32595946, 2020). "Since AR is central to prostate cancer progression and is a main therapeutic target in treating prostate cancer, any alteration in AR signaling can alter efficacy of these regimens." (PMID 32316460, 2020).
prostate carcinoma (continued). "Recent findings about multiple growth-promoting and survival pathways in advanced prostate cancer suggest the presence of alternative mechanisms involved in disease progression, and an interplay between these pathways and AR signalling." (PMID 35582226, 2020). "Resistance to androgen receptor (AR) targeting therapeutics in prostate cancer (PC) is a significant clinical problem." (PMID 32324216, 2020). "Our analysis found that dysregulation of AR signaling in prostate cancer driven by enzalutamide treatment increases the inclusion of exon-2 of the PLA2G2A gene in prostate cancer cells." (PMID 32820253, 2020). "Our findings raise the significant possibility that G4-stabilizing drugs can be used to increase NCL transcriptional repressor activity to block AR expression in prostate cancer." (PMID 32477465, 2020). "Because anti-hormonal treatment in prostate cancer is a systemic therapy, one cannot disregard that this regulation has also an effect in AR-expressing cells other than prostate cancer cells." (PMID 31947623, 2020). "Androgen receptor (AR) signaling is a critical survival pathway for prostate cancer cells, and androgen-deprivation therapy (ADT) through medical or surgical castration is the mainstay treatment for patients with locally advanced and metastatic disease." (PMID 33255236, 2020). "Beyond the role of the androgen receptor in driving cancer cell proliferation, previous work in prostate cancer and breast cancer has demonstrated the role of AR in mediating DNA repair and in the DNA damage response following radiation therapy." (PMID 32117061, 2020). "The signaling of androgen receptor is related to the progression of prostate cancer and considered as a therapeutical target for estrogen receptor-negative breast cancer." (PMID 32850805, 2020). "Current treatments for locally advanced and metastatic prostate cancer are mainly focused on targeting the androgen receptor (AR)." (PMID 33260953, 2020). "In this context, the newly identified inhibitory potential of C-1311 against the AR makes this drug a valuable candidate for further testing against prostate cancer." (PMID 32825120, 2020). "AR signaling has also been shown to stimulate MYC in AR-driven prostate cancer, while in normal prostate tissue AR silences MYC to maintain normal homeostasis." (PMID 32630372, 2020). "The tumor-promotingactivity of EZH2 in castration-resistant prostate cancer is mediated by its activityas a coactivator for AR." (PMID 32453339, 2020). "AR splice variants have been shown to require expression of full-length AR (AR-FL) suggesting that a balance between ARV and AR-FL expression is required for resistance in prostate cancer models." (PMID 33062889, 2020). "Nonetheless, both the AR and Tip60 are undeniably master regulators of the metabolic network in prostate cancer and they continue to constitute potential avenues for novel therapeutic options in androgen-sensitive prostate cancer." (PMID 32927797, 2020). "Similar to the role that AR plays in prostate cancer development and progression, the ER has been recognized for the integral role that it plays in driving the development of the majority of breast cancers." (PMID 33062889, 2020). "Wnt/β-catenin inhibitor can increase sensitivity of androgen-independent prostate cancer cells to the second-generation androgen receptor antagonist, enzalutamide, suggesting the therapeutic potential of this approach." (PMID 32904490, 2020). "BET proteins are therapeutic targets in different tumor types, but are of particular interest in prostate cancer because they affect the expression and activity of the AR pathway." (PMID 33134178, 2020).
prostate carcinoma (continued). "To further investigate cell line-dependent effects, we validated MF-15 in two other AR-positive prostate cancer cell lines." (PMID 32731472, 2020). "Androgen receptor (AR) signalling drives neoplastic growth and therapy resistance in prostate cancer." (PMID 32989230, 2020). "In this study we demonstrate that androgen-activated AR promotes the expression of Twist1 in prostate cancer cells." (PMID 32296610, 2020). "Many studies indicate that ubiquitination contributes to both AR degradation and AR transcriptional activity which is dependent on ubiquitinated residues [20,], and some ubiquitin E3 ligases targeting AR have been identified in prostate cancer." (PMID 31896509, 2020). "The androgen receptor (AR) is a ligand activated transcription factor involved in the progression of prostate cancer." (PMID 32180937, 2020). "A crucial aspect is the selection of proteins which play a major oncogenic role in a certain tumor type, as is the case of the AR in prostate cancer or the ER in breast cancer." (PMID 32933565, 2020). "In prostate cancer, FLNA binding promoted androgen receptor (AR) localization to the nucleus, promoting prostate cancer progression, but once in the nucleus, it inhibited the transcriptional activity of the same transcription factor." (PMID 32545553, 2020). "Recent studies have reported that IL-1 expression by prostate cancer cells is inversely correlated with AR activity and androgen deprivation can induce production of IL-1, leading to a pro-inflammatory tumor microenvironment." (PMID 33076397, 2020). "Most notably, the role of the androgen receptor (AR) in prostate cancer has been extensively studied." (PMID 33062889, 2020). "Androgen receptor signalling strongly promotes growth, proliferation and invasiveness of prostate cancer." (PMID 32056047, 2020). "Androgen receptor (AR) drives prostate cancer by regulating specific programs critical for tumor survival and growth." (PMID 32477465, 2020). "AR is the central signaling pathway in normal growth of the prostate gland and is frequently overexpressed during prostate cancer progression." (PMID 31935919, 2020). "This is supported by the effect of N-Myc upregulation on driving the formation of a neuroendocrine tumor type that differs from c-Myc-driven prostate cancer in histology and response to androgen receptor (AR) signaling-targeted therapies." (PMID 32547946, 2020). "The androgen receptor is an important therapeutic target in the treatment of prostate cancer, but recent studies have shown that it can also have a therapeutic and prognostic value in BC." (PMID 32373367, 2020). "Since AR collaborative TFs fine-tune androgen-responsive gene expression, it is important to further elucidate their role in the progression of prostate cancer." (PMID 33134178, 2020). "AR activation enhances glucose metabolism, including glycolysis, tricarboxylic acid cycle and oxidative phosphorylation, as well as lipid metabolism in prostate cancer." (PMID 32927797, 2020). "Our goal was to redirect AR in prostate cancer to promote differentiation over proliferation by identifying compounds that selectively inhibit AR action on genes driving cancer but not normal growth." (PMID 32198885, 2020). "Localized prostate cancer develops very slowly in most men, with the androgen receptor (AR) and MYC transcription factors amongst the most well-characterized drivers of prostate tumorigenesis." (PMID 32681068, 2020). "Androgen receptor (AR) signaling is fundamental to prostate cancer (PC) progression, and hence, androgen deprivation therapy (ADT) remains a mainstay of treatment." (PMID 31940946, 2020). "Although AR signaling is important for normal prostate tissue homeostasis, its overactivation is well established to be involved in prostate cancer formation." (PMID 33182828, 2020). "ERa was exhibited at the plasma membrane of the apical pole in prostate cancer epithelium co-expressing nuclear AR." (PMID 33266334, 2020).